RAF1 (Raf-1 proto-oncogene, serine/threonine kinase)
Diseases named in the same sentence as RAF1 in open-access papers (continued):
Sharing a sentence is not in itself a finding about the gene and the disease.
pancreatic ductal adenocarcinoma (5 papers, 2014 to 2023). An infiltrating adenocarcinoma that arises from the epithelial cells of the pancreas. "The lncRNA ITGB2-AS1 promoted pancreatic ductal adenocarcinoma progression by upregulating RAF1 through sequestering miR-4319." (PMID 38111008, 2023).
atherosclerosis (4 papers, 2013 to 2023). A disease characterized by the build-up of fatty material and calcium deposition in the arterial wall resulting in partial or complete occlusion of the arterial lumen. "And it has been reported that RAF1 deficiency could ameliorate atherosclerosis in mice." (PMID 24312440, 2013). "Rcan1 thus appears to promote atherosclerosis without interfering with CN activity, perhaps through its interaction with other Rcan1-interacting proteins implicated in gene activation, such as Raf-1, 14-3-3 and NF-kB-inducing kinase." (PMID 24127415, 2013). "ATK2, IKBKB, RAF1, CHUK, TNF, JUN, and PRKCA were mainly involved in fluid shear stress and the atherosclerosis pathways, pathways in cancer, and the PI3K-Akt signaling pathway." (PMID 29177114, 2017). "The targets of ATK2, IKBKB, RAF1, CHUK, TNF, JUN, and PRKCA were mainly involved in fluid shear stress and the atherosclerosis and PI3K-Akt signaling pathways." (PMID 29177114, 2017).
Cerebral ischemia (4 papers, 2013 to 2024). Restriction of arterial blood supply to the brain associated with insufficient oxygenation to support the metabolic requirements of the tissue. "RELA, AKT1, JUN, PRKACA, PTGS2, RAF1 and CHUK were identified as four key targets associated with ischemic encephalopathy." (PMID 38285889, 2024). "For example, during brain ischemia/reperfusion, intracellular signaling cascades were stimulated and interacted, which involved PI3K/AKT, Raf-1 and ERK1/2." (PMID 32161541, 2020).
Costello syndrome (4 papers, 2012 to 2025). "HRAS alterations were detected in only 2 out of 19 patients referred with a Costello syndrome suspicion, whereas pathogenic variants in RAF1 and SHOC2 were detected in 3 and 2, respectively." (PMID 37568403, 2023). "The remaining genes involved were RAF1 (three patients, all with Costello syndrome suspicion), RIT1 (two patients), BRAF (one patient), MAP2K1 (three patients), MAP2K2 (two patients), PTPN11 (two patients), SOS1 (one patient), and SHOC2 (three patients, two of them with Costello syndrome suspicion)." (PMID 37568403, 2023).
diabetes (4 papers, 2007 to 2023). "Here we provide exciting in vitro and in vivo data, showing that inhibition of superoxide, either by superoxide mimetic or by overexpression of MnSOD inhibits diabetes-induced activation of Raf-1 in the retina." (PMID 17515880, 2007). "This clearly suggests that the Ras-mediated detrimental effects on retinal capillary cells in diabetes are via Ras-Raf-1 pathway." (PMID 17515880, 2007). "Inhibition of diabetes-induced activation of H-Ras, Raf-1, and phosphorylation of p-p38 MAP kinase suggests that H-Ras activation in the retina could contribute to the development of diabetic retinopathy via activating Ras/Raf/MAP kinase signaling pathway." (PMID 17515880, 2007). "We have shown that in diabetes, Raf-1 is increased in the retina." (PMID 17515880, 2007). "Induction of oxidative stress by exposure to H2O2 increased activation of H-Ras and its Raf-1-mediated downstream signaling pathway in retinal endothelial cells, and overexpression of MnSOD prevented diabetes-induced activation of H-Ras and its signaling steps." (PMID 17515880, 2007).
diabetic retinopathy (4 papers, 2008 to 2024). "RAF1 activation by AGEs induces oxidative stress and inflammation in vascular endothelial cells, contributing to diabetic retinopathy." (PMID 38904047, 2024). "The purpose of this study is to investigate the role of Raf-1 in the development of diabetic retinopathy-by modulating the effect of Raf-1 kinase (inhibition and activation) on glucose-induced accelerated apoptosis of retinal endothelial cells." (PMID 23675062, 2008). "The purpose of this study is to investigate the role of Raf-1 in the development of diabetic retinopathy." (PMID 23675062, 2008). "The role of RAF1 has been studied in diabetic retinopathy, and here we provide insights into how RAF1 may connect with RP, which has seldom been noticed previously." (PMID 37372984, 2023).
endometriosis (4 papers, 2008 to 2025). The growth of functional endometrial tissue in anatomic sites outside the uterine body. "For example, USP10 promotes proliferation and migration and inhibits apoptosis of endometrial stromal cells in endometriosis by activating the Raf-1/MEK/ERK pathway." (PMID 33133065, 2020). "Alterations in cell deformability have been associated to cell-related diseases (e.g., malaria, sickle cell disease, and cancer) and, in particular, to endometriosis in relation to the Raf-1/Rho/ROCKII pathway, which are key regulators of the cytoskeleton structure." (PMID 40391170, 2025). "Activation of the MAPK pathway in endometriosis has also been suggested following the observation that PDGFR, PDGF, and RAF1, are highly elevated in this disease." (PMID 19055724, 2008).
influenza (4 papers, 2011 to 2024). An acute viral infection of the respiratory tract, occurring in isolated cases, in epidemics, or in pandemics; it is caused by serologically different strains of viruses (influenzaviruses) designated A, B, and C, has a 3-day incubation period, and usually lasts for 3 to 10 days. "And we found that there were the same target proteins in the tuberculosis pathway and influenza pathway, such as Raf1, CytC, ERK1/2, IL12 and p38." (PMID 25973739, 2015). "Pretreatment of HUVECs with Raf-1 inhibitor, GW 5074, phospholipase C inhibitor, U73122 and MEK/ERK inhibitor, PD98059 attenuated influenza-induced MLC phosphorylation." (PMID 21731751, 2011).
left ventricular hypertrophy (4 papers, 2014 to 2022). Enlargement of the LEFT VENTRICLE of the heart. "NS patients with kinase-activating RAF1 alleles typically develop pathological left ventricular hypertrophy (LVH), which is reproduced in Raf1L613V/+ knock-in mice." (PMID 28548091, 2017). "Patients with RAF1 mutations were characterized by left ventricular hypertrophy (obstructive or not obstructive), ASD and mitral regurgitation." (PMID 35770001, 2022).
liver disease (4 papers, 2016 to 2024). "Moreover, mitochondrially associated HBx also leads to activation of transcription factors STAT-3 and NF-κB and mitochondrial translocation of Raf-1 via oxidative stress, which is relevant to liver disease pathogenesis." (PMID 26950437, 2016). "In addition, analyses of gene-specific diurnal variations in levels of H3K27ac and H3K9ac of liver disease-driving genes (XBP1 and RAF1) and CC-component CRY1 confirmed the HCV-induced epigenetic perturbations." (PMID 39209804, 2024).
metastatic disease (4 papers, 2020 to 2023). "In cases of the APPL2-RAF1 fusion, RAF1 inhibitor use is recommended if metastatic relapse occurs, because the fusion was continuously detected from three recurrence and metastatic tumors after the initial tumor was identified." (PMID 36033527, 2022).
pulmonary stenosis (4 papers, 2019 to 2023). "Based on the genotype-phenotype associations observed during follow-up, BRAF and RAF1 genotypes seem to be poor prognostic factors, and multiple interventions may be required for NS patients with severe pulmonary stenosis or myectomy for HCM." (PMID 35770001, 2022). "HCM and pulmonic stenosis are the most common cardiac abnormalities in RAF1 mutation carriers." (PMID 31030682, 2019).
pulmonary valve stenosis (4 papers, 2022 to 2025). The pathologic narrowing of the orifice of the pulmonary valve. "RAF1 was another commonly mutated gene, often associated with HCM and negatively associated with pulmonary valve stenosis." (PMID 35770001, 2022). "Among all the pathogenic variants, we found that patients with mutations in RIT1, SOS1, PTPN11, and SOS2 had common echocardiography figures characterized by pulmonary valve stenosis, while RAF1 patients had HCM." (PMID 35770001, 2022). "RIT1, SOS1, PTPN11, and SOS2 had common echocardiography features characterized by pulmonary valve stenosis, while RAF1 was characterized by HCM." (PMID 35770001, 2022).
spindle cell neoplasm (4 papers, 2022 to 2025). A benign or malignant neoplasm characterized by the presence of neoplastic spindle cells. "Undifferentiated spindle cell neoplasms with NTRK-rearrangement (or activating mutations in RAF1, BRAF, RET, MET, and others) are rare, recently described lesions in children." (PMID 40491214, 2025). "Interestingly, other spindle cell tumors harboring RAF1, BRAF, and NTRK1/2 fusions and further characterized by S100 and CD34 co-expression (discussed hereafter, see Section 2.3), demonstrate a close proximity to some infantile fibrosarcomas by RNA unsupervised hierarchical clustering analysis." (PMID 35565289, 2022). "Recently, a novel group of CD34 and S100 co-expression spindle cell tumors with distinctive stromal and perivascular hyalinization harboring recurrent gene fusions involving RET, RAF1, BRAF, and NTRK1/2 gene has been identified." (PMID 36229858, 2022).
squamous cell carcinoma (4 papers, 2013 to 2023). A carcinoma arising from squamous epithelial cells. "However, as reported for other BRAF inhibitors, dabrafenib also induced MAPK pathway activation in wild-type BRAF cells through CRAF (RAF1) signalling, potentially explaining the squamous cell carcinomas and keratoacanthomas arising in patients treated with BRAF inhibitors." (PMID 23844038, 2013).
asthma (3 papers, 2012 to 2024). "Experiments of in vivo treatment with Raf-1 inhibitor and Raf/ERK/MAPK phosphorylation reveal that this pathway is involved in receptor upregulation (5-HT2A and ETA) process and bronchial hyperreactivity." (PMID 22952915, 2012).
bladder tumors (3 papers, 2023 to 2024). "For instance, using data obtained from the GENIE v3 cohort, we observed that RAF1 amplifications occur in bladder tumors at a frequency of 3.8% (139 out of 3844 patients), a rate higher than that for RAF1 amplifications in any other tumor type within this cohort." (PMID 38111008, 2023).
brain tumors (3 papers, 2022 to 2023). "Although RAF1 aberrations are infrequent in advanced solid cancers, RAF1 fusions have been previously identified in several solid tumors especially pediatric brain tumors and pancreatic acinar cell carcinomas." (PMID 38137485, 2023). "In conclusion, our studies suggest that the circXPO1/miR-7-5p/RAF1 axis promotes brain tumor formation and may be a potential therapeutic target for GBM treatment." (PMID 36980172, 2023).
chondrosarcoma (3 papers, 2015 to 2020). A malignant cartilaginous matrix-producing mesenchymal neoplasm arising from the bone and soft tissue. "Activation of Ras, Raf-1, MEK1 and ERK appears to be involved in S1P-induced AP-1 activation in human chondrosarcoma cells." (PMID 31809267, 2019). "Taken together, these data suggest that activation of Ras, Raf-1, MEK1, and ERK are required for AR-induced AP-1 activation in human chondrosarcoma cells." (PMID 25825984, 2015).
chronic lymphocytic leukemia (3 papers, 2019 to 2025). "Similarly, another study showed that suppression of circ-RPL15 inhibits the RAS/RAF1/MEK/ERK pathway via miR-146b-3p This interaction indicates a connection between RAF1, miR-146b-3p, and Circ-RPL15 in chronic lymphocytic leukemia (CLL)." (PMID 40727567, 2025).
chronic myeloid leukemia (3 papers, 2016 to 2024). "GRB10 interacts with oncogenic Bcr-Abl in chronic myelogenous leukemia, and with active Raf-1 to promote cell survival, and it also binds with FLT3 to enhance AML cell proliferation, which is suggestive of oncogenicity." (PMID 27977763, 2016). "Recently, our group reported that the Hsp70-Bim dimer recruits the oncogenic clients AKT, Raf-1, and eIF4E and mediates eIF2 signaling, the regulation of eIF4E and p70S6K signaling, and mTOR signaling pathway activation s to support chronic myeloid leukemia (CML) cell survival." (PMID 37237369, 2023). "The Hsp70–Bim dimer is a specific target activated by BCR–ABL in chronic myeloid leukemia that can lead to TKI resistance by stabilizing downstream kinases such as AKT and Raf-1." (PMID 38791529, 2024).
Cognitive impairment (3 papers, 2022 to 2024). Abnormal cognition is characterized by deficits in thinking, reasoning, or remembering. "In line with intellectual impairments, similar disabilities were found in the adaptive and behavioral functioning in very small samples of patients with variants of RAF1, compared with patients with variants in PTPN11 or SOS1." (PMID 36012976, 2022). "IQs were significantly lower in patients with variants in PTPN11, KRAS, RAF1, and SHOC2, but no specific cognitive impairments were found." (PMID 36012976, 2022).
Huntington disease (3 papers, 2012 to 2022). Huntington disease (HD) is a rare neurodegenerative disorder of the central nervous system characterized by unwanted choreatic movements, behavioral and psychiatric disturbances and dementia. "Abnormal activation of RRAS and a down-stream effector, RAF1, was observed in cellular models and a mouse model of Huntington's disease." (PMID 23209424, 2012).
Insulin resistance (3 papers, 2023 to 2024). Increased resistance towards insulin, that is, diminished effectiveness of insulin in reducing blood glucose levels. "Collectively, 3HB ameliorates insulin resistance in type 2 diabetic mice through a pathway of HCAR2/Ca2+/cAMP/PKA/Raf1/ERK1/2/PPARγ." (PMID 37230992, 2023). "Based on present in vitro results, we propose for the first time that 3HB regulates ERK1/2 activity via HCAR2/Ca2+/cAMP/PKA/Raf1, optimizing PPARγ function from the aspect of post-translational modification to reduce insulin resistance." (PMID 37230992, 2023). "3-Hydroxybutyrate, originating from the increased β-oxidation of free fatty acids, is found in higher concentrations in the plasma of T2DM patients and has been shown to ameliorate insulin resistance in T2DM mice through the HCAR2/Ca2+/cAMP/PKA/Raf1/ERK1/2/PPARγ pathway." (PMID 38184583, 2024). "The pathway of 3HB/HCAR2/Ca2+/cAMP/PKA/Raf1/ERK1/2/PPARγ might be the molecular mechanism by which 3HB ameliorates insulin resistance." (PMID 37230992, 2023). "At the same time, this paper further explored the molecular mechanism of 3HB decreasing insulin resistance level, which is by indirectly inhibiting the phosphorylation of PPARγ Ser273 site through HCAR2/Ca2+/cAMP/PKA/Raf1/ERK1/2/PPARγ signaling pathway." (PMID 37230992, 2023).
metastatic melanoma (3 papers, 2019 to 2023). A melanoma that has spread from its primary site to another anatomic site. "One major challenge in treating metastatic melanoma with BRAF-inhibitors is the 13 development of resistance secondary to upregulation of other proteins in the Ras-Raf-MEK14 MAPK pathway, such as RAF1 (C-RAF) or RAS." (PMID 31803366, 2019).
multiple myeloma (3 papers, 2012 to 2025). "The analysis revealed that our models identified probes associated with genes involved in pathways closely related to multiple myeloma, such as PI3K-Akt, MAPK, Wnt signaling, BRAF and RAF1 fusion signaling, and mTOR pathways." (PMID 39858113, 2025).
pancreatic adenocarcinoma (3 papers, 2015 to 2024). "Furthermore, we mined sequencing data for 126 pancreatic adenocarcinoma patient-derived xenograft (PDX) models and identified an additional KRAS wild-type tumour with a PDZRN3-RAF1 fusion, which conserves the RAF1 kinase domain." (PMID 31097696, 2019).
small cell lung carcinoma (3 papers, 2020 to 2022). Small cell lung cancer (SCLC) is a highly aggressive malignant neoplasm, accounting for 10-15% of lung cancer cases, characterized byrapid growth, and early metastasis. "Tobacco carcinogen NNK can activate a Raf-1/MAP kinase pathway and stimulate cell proliferation in human small cell lung carcinoma cells, while sphingosine might block this process." (PMID 33213368, 2020). "As a consequence of FGF2 stimulation, PKCε complex formation with BRAF and S6K2, but not with S6K1 and RAF-1, induced drug resistance in SCLC (small cell lung cancer) cells, HEK293 and U2OS cells." (PMID 34830951, 2021).
soft tissue sarcoma (3 papers, 2018 to 2025). A malignant neoplasm arising from muscle tissue, adipose tissue, blood vessels, fibrous tissue, or other supportive tissues excluding the bones. "In a previous study, RAF1 fusions were reported in soft tissue sarcoma, in which the fusion counterparts, PDZRN3, SLMAP and TMF1, were identified in three of eight cases." (PMID 32825119, 2020). "Another case report has been published which revealed a novel MTAP-RAF1 fusion in a 51-year-old male patient which included the tyrosine kinase domain of RAF1 in a patient with soft tissue sarcoma (not otherwise specified) of foot." (PMID 40556788, 2025).
Ventricular arrhythmia (3 papers, 2022 to 2025). "Therefore, it is crucial to understand the role of RAF1 variants in AF pathophysiology through cardiac electrophysiology alterations given the association between RAF1 variants and ventricular arrhythmias." (PMID 40625395, 2025).
ameloblastoma (2 papers, 2022 to 2024). The most common odontogenic tumor, arising from the epithelial component of the embryonic tooth and usually affecting the molar-ramus region of the mandible or maxilla. "For instance, ARL4C expression dependent on the RAF1-MEK/ERK pathway promotes ameloblastoma cell proliferation and osteoclast formation." (PMID 39268462, 2024).
astrocytoma (2 papers, 2019 to 2021). "We detected that 18 genes were respectively correlated with overall survival in astrocytoma; moreover, four genes (RAF1, AKT3, IDH1, and FGFR1) were detected as dependent variables for the prediction of the survival status of astrocytoma patients and were capable to predict the survival." (PMID 31620163, 2019). "Based on the ranking results, four genes (RAF1, AKT3, IDH1, and FGFR1) were independent predictors of the survival status of astrocytoma patients." (PMID 31620163, 2019).
atopic dermatitis (2 papers, 2016 to 2024). "Dry skin is indeed listed as one of the side effects–interestingly, the association between this phenotype and the drug is mediated by the proteins coded for by genes RAF1 and BRAF, both of which have been linked with atopic dermatitis in previous work." (PMID 39911831, 2024). "Here, we systematically test the effect of compound BRAF/RAF1 ablation in epidermis and show that it gives rise to a progressive disease strongly resembling human atopic dermatitis." (PMID 27431613, 2016). "Mice lacking BRAF/RAF1 in keratinocytes develop a disease clinically very similar to human atopic dermatitis." (PMID 27431613, 2016).
atrial septal defect (2 papers, 2021 to 2025). Interauricular communication is a congenital malformation characterized by a communication between the atrial chambers of the heart. "PTPN11 variants were linked to PS and atrial septal defects, SOS1 to multiple cardiopathies, and RAF1 to HCM." (PMID 40332000, 2025). "For example, in the case of atrial septal defect (ASD) and ventricular septal defect (VSD), candidate genes can be counted: NKX2-5, GATA4, TBX20, MYH6, and TBX5, while the pathogenesis of atrioventricular septal defect (AVSD) involves genes, such as PTPN11, KRAS, SOS1, RAF1, and CRELD1." (PMID 34946970, 2021).
B cell lymphoma (2 papers, 2006 to 2023).
colorectal adenocarcinoma (2 papers, 2015 to 2021). The most common type of colorectal carcinoma. "A similar trend was observed in SW480 colorectal adenocarcinoma cells upon knockdown of MAPK1 (ERK2) or RAF1 (c-RAF/Raf-1) genes, highlighting the involvement of mitogen-activated protein kinases (MAPKs) in the regulation of GPR55." (PMID 34948125, 2021).